SOCS3 (suppressor of cytokine signaling 3)
Diseases named in the same sentence as SOCS3 in open-access papers (continued):
Sharing a sentence is not in itself a finding about the gene and the disease.
leukemia (14 papers, 2013 to 2025). A malignant (clonal) hematologic disorder, involving hematopoietic stem cells and characterized by the presence of primitive or atypical myeloid or lymphoid cells in the bone marrow and the blood. "In CLL, the expression of the SOCS3 is suppressed and significantly associated with leukemia progression." (PMID 40075418, 2025). "Abnormal expression of SOCS3 has been implicated in myeloproliferative neoplasms, but the role of SOCS3 in the pathogenesis of leukemia remains largely unknown." (PMID 27516205, 2016). "Treatment with this compound increases the levels of SOCS1 and SOCS3 in myeloproliferative neoplasms (MPNs) and leukemia." (PMID 35611249, 2022). "Validating the results showing upregulated gene expression, we observed an increase in the expression of SOCS1 and SOCS3 proteins in leukemia cells from PDX-1, PDX-2, Mutz-5, and Call-4." (PMID 36613920, 2022). "In similarity, our findings revealed that the cell proliferation inhibition of HL60 leukemia cells was associated with a significant re-expression of SHP-1, SOCS-1, and SOCS-3 genes after exposure to 2 μM TQ." (PMID 33773553, 2021). "SOCS3 expression was also ablated in Lck LSTRA leukemia, with enforced ectopic expression of SOCS3 reducing cell proliferation and increasing apoptosis in Lck-transformed cells." (PMID 34604264, 2021). "Taken together, the findings of the present study indicate that TQ induced cell proliferation inhibition of HL60 leukemia cells with a cell cycle arrest in early stages, and apoptosis induction associated with re-expression of SHP-1, SOCS-1, and SOCS-3 genes." (PMID 33773553, 2021). "Taken together, these results show that BRD9 is a key regulator for STAT5 activation in leukemia via regulation of SOCS3 expression." (PMID 31000698, 2019). "We measured the expression of SOCS3 by qPCR in a panel of human leukemia cell lines and primary bone marrow mononuclear cells (BMNCs) from healthy donors (n = 3)." (PMID 27516205, 2016). "Here, we found that over-expression of SOCS3 in CML cells induced a transcriptional program enriched for leukemia suppression factors, including some miRNAs." (PMID 27516205, 2016). "Previous studies demonstrated that the expression of SOCS3 was associated with the response of CML cells to IFN-alpha, and down-regulation of SOCS3 was a possible reason for imatinib resistance of leukemia cells." (PMID 27516205, 2016). "Expression levels of SOCS3 in several leukemia cell lines and bone marrow mononuclear cells (BMNCs) from CML patients were determined using quantitative real-time PCR (qPCR) and Western blotting (WB)." (PMID 27516205, 2016). "Over-expression of SOCS3 in K562 cells inhibited the expression of leukemia-specific genes and promoted the expression of some miRNAs, among which miR-124-3p was the highest." (PMID 27516205, 2016). "Furthermore, sodium butyrate treatment increases the transcript levels of SOCS1 and SOCS3 and inhibits cell proliferation in myeloproliferative neoplasms (MPNs) and leukemia." (PMID 35611249, 2022). "Furthermore, upregulation of SOCS3 expression levels was relevant to T dysfunction in leukemia (GSE12417_GPL570)." (PMID 35600392, 2022). "The restoration of SHP-1, SOCS-1, and SOCS-3 expression by epigenetic modulating agents such as 5-azacytidine (5-Aza) was associated with significant inhibition of JAK2/STAT3 and STAT5 signaling in AML leukemia cells." (PMID 34959687, 2021). "We found that SOCS3 expression was down-regulated in human leukemia cells, with the lowest expression levels in K562 cells, indicating that SOCS3 could be down-regulated in CML." (PMID 27516205, 2016). "Evidence suggests a potential role of SOCS3 in the pathogenesis of leukemia." (PMID 27516205, 2016). "In this study, the authors examined the effects of TQ on the expression of JAK/STAT-negative regulator genes SOCS-1, SOCS-3, and SHP-1, and their consequences on cell proliferation and apoptosis in HL60 leukemia cells." (PMID 33773553, 2021).
leukemia (continued). "SOCS-1 and SOCS-3 genes are also negative regulators of JAK/STAT pathway, were down-regulated in MV4-11 leukemia cells and their re-expression by demethylation was associated with inhibition of JAK/STAT signaling and lower cell proliferation." (PMID 33773553, 2021). "A significant proportion of unmutated STAT3 LGL leukemia cases also features hyperactivation of the JAK/STAT pathway by two mechanisms; i) underexpression of the SOCS3 (suppressor of cytokine signaling-3) gene, ii) excess autocrine production of interleukin-6 by NK-LGLs." (PMID 35178350, 2022). "Additionally, the expression of JAK/STAT-negative regulator genes, SHP-1, SOCS-1, and SOCS-3 genes, was investigated before and after treating HL60 leukemia cells with TQ." (PMID 33773553, 2021). "TQ also induced hypomethylation of SHP-1 promotor 2 region and SOCS-3 promoter region in K562 leukemia cells (Data not shown)." (PMID 34959687, 2021). "We found that SOCS3, but not SOCS2, was highly expressed in leukemic blood and bone marrow, while leukemia/lymphoma cell lines lacking PCM1-JAK2, including acute eosinophilic leukemia, expressed neither gene." (PMID 23372669, 2013).
liver fibrosis (14 papers, 2016 to 2025). "Thus, we found that PBMCs from individuals at moderate-to-high risk of liver fibrosis exhibited significantly lower DNA methylation levels at specific CpG sites within the SOCS3 gene locus compared to PBMCs from subjects at low risk of fibrosis." (PMID 39941038, 2025). "We focused on SOCS3, SREBF1, and TXNIP, genes known to be implicated in inflammatory pathways and liver fibrosis." (PMID 39941038, 2025). "Suppression of SOCS3 contributes to liver fibrosis by increasing fibrogenic signaling via STAT3-mediated upregulation of tissue growth factor (TGF)-β." (PMID 36303554, 2022). "Overall, we demonstrate that S. japonicum infection or SEA stimulates hepatic Mφ to secrete abundant EVs, which are enriched with miR-33 and transferred to neighboring HSCs to enhance their autocrine TGF-β1 production and activation by targeting SOCS3 and ultimately promote liver fibrosis." (PMID 37253066, 2023). "Briefly, schistosome egg antigen (SEA) induces Mφ to secrete abundant miR-33-enriched EVs, which are transferred to enhance autocrine TGF-β1 production by targeting SOCS3 in HSCs, thereby promoting HSC activation and liver fibrosis." (PMID 37253066, 2023). "The suppressor of the cytokine signaling-3 (SOCS3) has been reported to negatively regulate TGF-β1 production and liver fibrosis." (PMID 37253066, 2023). "It has been demonstratedthat SOCS3 deletion in the liver resulted in hyperactivation of STAT3 and promotedchemical-induced liver fibrosis." (PMID 34450627, 2021). "Deletion of the suppressor of cytokine signaling-3 (SOCS3) gene in mice injected with dimethylnitrosamine, a drug known to induce liver fibrosis, resulted in increased activation of STAT3 in liver cells." (PMID 30072615, 2018). "Moreover, hypermethylation of the suppressor of cytokine signaling‐3 (SOCS3) gene promoter reduces SOCS3 expression, activating STAT3 and upregulating TGFβ‐1 expression, exacerbating liver fibrosis." (PMID 39462685, 2024). "The current study demonstrated that upon SEA stimulation Mφ secrete abundant EVs carrying miR-33 to promote HSC activation by targeting SOCS3 expression and activating autocrine TGF-β1 signaling in HSCs, thereby accelerating the progression of hepatic fibrosis." (PMID 37253066, 2023). "For example, absence of SOCS3 leads to the liver fibrosis by increasing the production of TGF-β that was mediated by STAT3." (PMID 34784837, 2021). "This is in line with the evidence of the central role of inflammatory pathways in liver fibrosis progression in MASLD and suggests that epigenetic changes affecting SOCS3 could impact the expression of cytokines primarily involved in inflammation and fibrogenesis, such as IL-6 and MCP-1." (PMID 39941038, 2025). "SOCS3, by virtue of its function of STAT3 signalling suppressor may also provide an anti-fibrotic contribution, as STAT3 promotes liver fibrosis, and increased gene expression of the anti-fibrotic fibronectin type III domain containing 5 (Fndc5, also known as irisin) was observed in the KD group." (PMID 35995402, 2022).
Hepatitis (12 papers, 2010 to 2023). Inflammation of the liver. "It has been demonstrated previously that T-cell specific overexpression of SOCS3 reduced expression of T-bet in T cells and protected from development of conA-induced hepatitis in mice." (PMID 25994622, 2015). "SOCS3 was protective against hepatitis-induced HCC, with loss of SOCS3 leading to reduced apoptosis and increased proliferation." (PMID 24757565, 2014). "Furthermore, forced expression of SOCS3 in T cells hasbeen shown to protect against the development of ConA-induced hepatitis." (PMID 21483776, 2011). "The expression level of suppressor of cytokine signaling 3 (SOCS3) in HCC cells decreases, and deletion of SOCS3 accelerates hepatocyte proliferation and promotes hepatitis-induced hepatocarcinogenesis." (PMID 35619714, 2022). "Kaplan–Meier curve analysis revealed that in patients with an hepatitis B virus (HBV) infection background, SOCS3 hypermethylation was significantly correlated with a poor clinical outcome of HCC patients." (PMID 26393582, 2015). "Conditional deletion of SOCS3 in T and NKT cells exacerbates ConA-induced hepatitis, while transgenic overexpression of SOCS3 in T and NKT cells or intraperitoneal administration of cell-penetrating SOCS3 in mice prevents ConA-induced liver injury." (PMID 20862390, 2010).
lung adenocarcinoma (12 papers, 2014 to 2025). A carcinoma that arises from the lung and is characterized by the presence of malignant glandular epithelial cells. "Hypoxic lung adenocarcinoma cells release exosomes containing high levels of miR-1290, which targets and inhibits the suppressor of cytokine signaling 3 (SOCS3)." (PMID 40496868, 2025). "A study showed that hypoxic lung adenocarcinoma cell-derived exosomes overexpressing miR-1290 can polarize M2 macrophages by targeting SOCS3, which further promote tumor progression." (PMID 38825680, 2024). "Recombinant SOCS3 delivered in synthetic liposomes inhibits in vitro proliferation and survival of lung adenocarcinoma cells and suppresses the malignant transformation of normal endothelial cells, suggesting its potential as a lung cancer treatment strategy." (PMID 38229178, 2024). "Administration of recombinant SOCS3 within synthetic liposomes inhibited proliferation and survival of lung adenocarcinoma cells in vitro, as well as attenuated tumor growth in a lung cancer xenograft model." (PMID 33915715, 2021). "BALF collected from patients with lung adenocarcinoma contained lower levels of SOCS3." (PMID 33915715, 2021). "AMs-derived extracellular vesicles containing SOCS3 inhibited STAT3 activation as well as proliferation and survival of lung adenocarcinoma cells." (PMID 38229178, 2024). "EVs derived from AMs containing SOCS3 significantly restrained STAT3 activation and reduced proliferation and survival of lung adenocarcinoma cells." (PMID 33915715, 2021). "It has been observed that Mycobacterium tuberculosis infection induces the expression of SOCS3 in phagocytes, which in turn stops STAT3 activation by inhibiting some of the STAT3-activating cytokine receptors, as well as proliferation and survival of lung adenocarcinoma cells." (PMID 35153741, 2021). "The lack of an inverse correlation between SOCS3 and IDO1 was confirmed using expression data of 215 human mature aggressive B-cell lymphomas and 204 lung adenocarcinomas." (PMID 24657910, 2014).
metabolic syndrome (12 papers, 2015 to 2024). A cluster of metabolic risk factors for CARDIOVASCULAR DISEASES and TYPE 2 DIABETES MELLITUS. "As another important signal leading to E3-ligase expression likely via the inhibition of Akt, SOCS3 has been implicated in cancer cachexia, age-related sarcopenia as well as metabolic syndrome." (PMID 35626644, 2022). "The association between the loss of SOCS3 and metabolic syndromes, including T2D, has been addressed previously by several groups." (PMID 36078084, 2022). "As an inhibitor of leptin and insulin signaling, increased muscular SOCS3 expression has been suggested as a major contributor to mitochondrial dysfunction, impaired fatty acid oxidation, as associated with aging, metabolic syndrome, and inflammation." (PMID 35151349, 2022). "The loss of SOCS3 expression is seen not only in diabetic settings but also in other metabolic syndromes, such as nonalcoholic fatty liver disease (NAFLD)." (PMID 36078084, 2022). "The analysis of the association of SNPs with T2DM demonstrated that SOCS3 and JAK2 genes may be associated with T2DM, whereas interaction between the SOCS3, JAK2, and STAT3 are related to metabolic syndrome features." (PMID 36674935, 2023). "Neuroinflammation, particularly in the aging hypothalamus, may contribute to metabolic syndrome, which is thought to be mediated through induction of hypothalamic NFκB or variable SOCS3 signaling in microglia." (PMID 30036185, 2018). "The association between previously reported SNPs on SOCS3 and the parameters of childhood obesity with or without Metabolic syndrome (MS) is not well-known." (PMID 27611604, 2016).
periodontitis (12 papers, 2013 to 2026). An acute or chronic inflammatory process that affects the tissues that surround and support the teeth. "SOCS3 deficiency results in increased alveolar loss with high levels of IL-1β, IL-6, and IL-8 in periodontitis." (PMID 31304055, 2019). "SOCS3 is regarded as an important negative regulator of alveolar bone loss in periodontitis." (PMID 36456933, 2022). "An inhibition of SOCS-3 expression during infection has been associated with an increased severity of inflammation in patients with Down syndrome (DS) and periodontitis in comparison to either euploid individuals affected by periodontal diseases or periodontally healthy euploid individuals." (PMID 28748038, 2017). "In HGEC infected with P. gingivalis, inhibition of SOCS-3 expression may represent a way by which the bacterium contributes to chronic inflammation associated with periodontitis." (PMID 28748038, 2017). "Taken together, SOCS1, SOCS2 and SOCS3 genes have been found to be dysregulated in the circulation of patients with periodontitis." (PMID 36456933, 2022). "Mice with a null-mutation of Socs-3, the “Suppressor of Cytokine Signaling” (SOCS)-3 proteins, develop periodontitis when they are infected with P. gingivalis." (PMID 29163477, 2017). "Previously, our group analyzed the expression of SOCS1 and SOCS3 in ligature-induced periodontitis in rats." (PMID 24078776, 2013). "In this specific experimental periodontitis mouse model, the investigators have noted increased expression of RANKL and an increase in osteoclast activity; moreover, in line with the function of Socs-3, they showed an increased expression of pro-inflammatory cytokines such as IL-1β and IL-6." (PMID 29163477, 2017). "Interestingly, a previous history of periodontitis did not influence the methylation level of SOCS1, SOCS3, and LINE-1." (PMID 29201597, 2017).
ulcerative colitis (12 papers, 2010 to 2025). An inflammatory bowel disease involving the mucosal surface of the large intestine and rectum. "In inflammatory bowel disease, particularly Crohn’s disease and ulcerative colitis, SOCS3 modulates inflammation at various stages of the disease, with increased SOCS3 expression in macrophages and T cells linked to disease severity and inflammation control." (PMID 40104138, 2025). "Furthermore, recent studies show that STAT3 activation is increased, and SOCS3 is silenced in tumors of patients with ulcerative colitis-associated and sporadic CRC." (PMID 20500855, 2010). "The expression of phosphorylated-STAT3, signal transducer and activator of transcription 3, cyclin D1, and suppressor of cytokine signaling 3 was significantly increased in mice of ulcerative colitis model group compared to the control group (P < .05)." (PMID 35946886, 2022). "SOCS3 was found to limit inflammation-associated oncogenic transformation in the colon, via regulation of STAT3 and NFκB, while in ulcerative colitis, loss of SOCS3 expression was observed in the areas of colonic dysplasia." (PMID 24757565, 2014). "Interestingly, colonic tissue samples of patients with Crohn's disease demonstrated increased STAT1 phosphorylation levels and, compared to samples taken from ulcerative colitis patients, increased SOCS3 levels." (PMID 24710357, 2014). "Increased SOCS3 expression has been detected in mouse models of IBD and in biopsies of ulcerative colitis patients where it seems to limit the extent of inflammation." (PMID 32824269, 2020).
inflammatory bowel disease (11 papers, 2014 to 2026). A spectrum of small and large bowel inflammatory diseases of unknown etiology. "Three complementary causal inference approaches support most sites as responding to IL-6, with SOCS3 (Suppressor of Cytokine Signalling 3) methylation statistically mediating inflammatory bowel disease risk." (PMID 41639309, 2026). "The role played by SOCS3 in human diseases has been investigated mainly in patients with inflammatory bowel disease (IBD), where SOCS3 mRNA and protein expression in bowel biopsies correlated with the severity of histological inflammation." (PMID 38533493, 2024). "These include inflammatory bowel disease (IBD) and its more severe phenotype, Crohns disease, with SOCS3 responsible for suppressing the activation of inflammatory genes induced by STAT3 during IBD." (PMID 34604264, 2021). "Approximately 10% of these macrophages express SOCS3 in healthy individuals, whereas in inflammatory bowel disease (IBD) patients this increases to 40%, again suggesting SOCS3 expression relates to M1-activated macrophages." (PMID 25120543, 2014). "Current studies demonstrated that in inflammatory bowel disease (IBD), SOCS3 acts on multiple cell types—including epithelial cells, macrophages, dendritic cells, neutrophils, and T cells—to repair mucosal damage and balance immune responses." (PMID 40613560, 2025). "SOCS3 targets diverse cytokine pathways by binding to receptors and JAKs and curbs signal transmission, moderating inflammation and immune responses in type 1 diabetes, inflammatory bowel disease (IBD), and psoriasis." (PMID 38022642, 2023). "IL-24 exerts anti-inflammatory effects in a variety of autoimmune diseases, including inflammatory bowel disease (IBD) and experimental autoimmune uveitis (EAU), by activating SOCS3." (PMID 38780647, 2024).